CACNA1C (calcium voltage-gated channel subunit alpha1 C)
Diseases named in the same sentence as CACNA1C in open-access papers (continued):
Sharing a sentence is not in itself a finding about the gene and the disease.
Brugada syndrome (32 papers, 2012 to 2026). "Mutations in the GPD1L (glycerol-3-phosphate dehydrogenase-1–like) gene and in the CACNA1C and CACNB2b (alpha and beta subunits of the L-type calcium channels) genes have been associated with Brugada syndrome." (PMID 41062843, 2026). "Subsequent international meetings held on topics of ultra-rare cardiac diseases have supported this opinion, based on insufficient case-level data and lack of functional validation evidencing an association between CACNA1C and Brugada Syndrome." (PMID 41333400, 2025). "In 2018 the Clinical Genome Resource (ClinGen) re-examined the gene-disease relationship for CACNA1C and Brugada Syndrome, and classified the evidence supporting a causal role for CACNA1C in Brugada Syndrome as limited." (PMID 41333400, 2025). "In this computational simulation study, we investigated pro-arrhythmic effects of loss-of-function missense mutations in CACNA1C (A39V and G490R Cav1.2) identified in patients with a phenotype combining Brugada syndrome with shorter-than-normal QT intervals." (PMID 41259367, 2025). "As a consequence, most of CACNA1C mutations are associated with cardiac arrhythmic and structural disorders such as long QT syndrome, Brugada syndrome, paroxysmal familial ventricular fibrillation or hypertrophic cardiomyopathy." (PMID 30984024, 2019). "It is also interesting this CACNA1C variant is enriched in Malays, as the arrhythmogenic sudden unexpected nocturnal death syndrome is especially common in South East Asians." (PMID 25184293, 2014). "Also, many mutations in CACNA1C have been linked to Brugada syndrome, a cardiac disorder that is characterized by ventricular arrhythmia." (PMID 24775099, 2014). "Besides well-described pathogenic variants in CACNA1C leading to TS, long QT syndrome (LQT), and Brugada syndrome (BrS), single nucleotide polymorphisms (SNPs) within CACNA1C have been described as one of the most replicable and consistent associations in psychiatric genetics." (PMID 36421807, 2022). "Variations in genes implicated in cardiac calcium signaling have been shown to cause a number of arrhythmia syndromes, including long-QT syndrome 4 (ANK2) and 8 (CACNA1C), Brugada syndrome (CACNA1C) and catecholaminergic polymorphic ventricular tachycardia (RyR2)." (PMID 27857207, 2016). "Short QT syndrome (SQTS) and Brugada Syndrome (BrS) were first reported in individuals with CACNA1C p.A39V and p.G490R variants in 2007, not long after the definition of TS, however the evidence for such variants as a genetic aetiology of SQTS and BrS is disputed." (PMID 41333400, 2025). "Besides the important pathogenic mechanism in TS, previous studies also found that functional gain and loss mutations of CACNA1C gene encoding Cav1.2 proteins are often associated with hereditary arrhythmia syndromes including non-TS long QT syndrome, Brugada syndrome and so on (Ref." (PMID 37132248, 2023). "In contrast, rare variants located in genes encoding calcium (CACNA1C, CACNA2D1, and CACNB2) and the SCN5A gene, have been associated with Brugada syndrome (BrS) concomitant with shortened QT intervals, but without a conclusive diagnosis of SQTS." (PMID 30420954, 2018). "Moreover, many ion channels, such as CACNA1C and SCN5A, are very sensitive to testosterone, and this could explain the gender difference in the prevalence of Brugada syndrome." (PMID 36617651, 2022).
heart failure (31 papers, 2007 to 2025). Inability of the heart to pump blood at an adequate rate to meet tissue metabolic requirements. "Expression for proteins responsible for excitation–contraction coupling (Atp2a2/Serca2a, Cav1.2/Cacna1c, Ryr2) was dysregulated in MI animals, consistent with pathological remodeling associated with MI and progression to heart failure." (PMID 37801130, 2023). "Moreover, a blunted positive-inotropic response to β-adrenergic stimulation, as seen in Cacna1c+/− myocytes, is also found in hypertrophy and heart failure, although the underlying cellular mechanisms may differ." (PMID 37372947, 2023). "Even less than a decrease of 50% in calcium current can lead to heart failure and enhance mortality in Cacna1c-knockout mice." (PMID 37448958, 2023). "Moreover, CACNA1C mRNA expression was dramatically downregulated in both dilated and ischemic cardiomyopathy failing hearts, implying that decreased CaV1.2 calcium channel may also be involved in the induction of hypertrophy and/or heart failure." (PMID 28949795, 2018). "However, other features of the Cacna1c+/− model clearly differ from the Ca2+ handling remodeling in hypertrophy and heart failure, such as the increased expression of SERCA (decreased in heart failure) or the lack of altered phosphorylation of RyR2 at S2814 (increased in heart failure)." (PMID 37372947, 2023).
long QT syndrome (30 papers, 2010 to 2025). "More recently, a wide variety of phenotypes in CACNA1C variant carrier have been reported, including those expressing only cardiac features or even long QT syndrome (LQT8) alone." (PMID 36347939, 2022). "Defects in gene CACNA1C, which encodes the pore-forming α1 subunit of the hCav1.2 channel, underlie cardiac disorders such as atrial fibrillation, long QT syndrome, conduction disorders, cardiomyopathies, and congenital heart defects." (PMID 34436362, 2021). "Several variants in the L-type calcium channel component CACNA1C have also been demonstrated to predispose for arrhythmic phenotypes, especially long-QT syndromes, while the gap junction protein encoded by TJP2 has been associated with hypertrophy in other cell types." (PMID 40791945, 2025). "His paternal cousin, diagnosed with Long QT syndrome, carries the CACNA1C variant." (PMID 41287789, 2025). "Timothy syndrome type 1 (TS1), a malignant variant of Long QT Syndrome, is caused by L-type Ca2+ Channel (LTCC) inactivation defects secondary to the p.Gly406Arg mutation in the CACNA1C gene." (PMID 39616198, 2024). "In tandem, the role of 9 genes for monogenic long QT syndrome (LQT1-9) was assessed, yielding evidence of association with CACNA1C (LQT8; p = 3.09 × 10-4; OR = 1.18, 95% CI:1.079, 1.290)." (PMID 21658281, 2011). "Mutations of SCN5A, CACNA1C and CAV3 are associated with ventricular tachycardia, long-QT syndromes (LQT3,8,9), and sudden cardiac death while mutations of HCN4 cause sick sinus syndrome type 2." (PMID 20300641, 2010). "The proband ́s paternal grandmother (II-2) with sinus tachycardia and mitral regurgitation also carries the CACNA1C variant, though she does not have Long QT syndrome either." (PMID 41287789, 2025). "As a consequence, functional alterations in Cav1.2 channels mainly due to CACNA1C gene mutations lead to cardiac arrhythmic disorders such as atrial fibrillation, long QT syndrome and conduction defects, as well as structural cardiac disorders such as cardiomyopathies and congenital heart defects." (PMID 30984024, 2019). "Thus, CACNA1C variants may be associated with non-syndromic hyperinsulinemic hypoglycemia without long-QT syndrome, explained by very specific electrophysiological properties of the mutated channel." (PMID 35897673, 2022).
cardiac hypertrophy (21 papers, 2007 to 2024). "Mutations in CACNA1C, which encodes CaV1.2, result in the pathogenesis of atrial fibrillation, ventricular fibrillation, hypertrophic cardiomyopathy and ventricular hypertrophy." (PMID 32290730, 2020). "The transcription of Kcnj5, Cacnb2 and Cacna1c was reduced in the hearts of mice with severe heart hypertrophy." (PMID 34201741, 2021). "Re-expression of the identified isoform by missplicing of the Cav1.2 gene, Cacna1c, promoted proteasomal degradation of wild-type Cav1.2, thus explaining the reported decreased expression and activity of Cav1.2 in cardiac hypertrophy." (PMID 30050558, 2018). "This study provides evidence that regulation of RNA splicing by Rbfox1 may play an important role in transcriptome reprogramming, including CACNA1C mRNA, during cardiac hypertrophy that influences the pathogenesis of the disease." (PMID 29186814, 2017). "In contrast, no change in Cacna1c or Kcnj5 mRNA could be observed in mice with heart hypertrophy but without upregulation of the two miRs (isoprenaline treatment)." (PMID 31312877, 2020).
epilepsy (21 papers, 2014 to 2025). A brain disorder characterized by episodes of abnormally increased neuronal discharge resulting in transient episodes of sensory or motor neurological dysfunction, or psychic dysfunction. "As more pathogenic mutations of CACNA1C are discovered, more epilepsy phenotypes caused by mutations in this gene have been reported." (PMID 41177904, 2025). "The variant identified in this study differs significantly from previously reported CACNA1C-related epilepsy mutations, with a milder clinical presentation and typical focal seizures associated with medial temporal lobe involvement." (PMID 41177904, 2025). "This is an interesting aspect because it motivated the search for CACNA1C mutations in case of clinical presentation of apraxia, ataxia and/or epilepsy, isolated or associated with each other." (PMID 38790536, 2024). "The CACN1C has potential pathogenicity in corresponding epilepsy; two families with CACNA1C mutation were presented with neonatal epileptic encephalopathy and/or epilepsy combined DD/ID." (PMID 34210021, 2021). "Given the limited reports associating CACNA1C mutations with epilepsy, while predictive tools and ACMG assessments provide valuable insights, they may not provide a definitive evaluation of pathogenicity." (PMID 41177904, 2025). "Previous studies have shown that pathogenic mutations in the CACNA1C gene are closely associated with various epilepsy phenotypes, including neonatal-onset epileptic encephalopathy (NOEE), generalized epilepsy, and focal epilepsy, with some cases exhibiting fever sensitivity." (PMID 41177904, 2025). "This study aimed to investigate the association of polymorphisms in CACNA1A, CACNA1C, and CACNA1H with DD/ID and epilepsy comorbidity in Korean children." (PMID 40725423, 2025). "This study aims to address this gap by investigating the frequency of selected SNPs in CACNA1A, CACNA1C, and CACNA1H in Korean children with DD/ID, and by evaluating their association with epilepsy comorbidity." (PMID 40725423, 2025). "A total of nine SNPs in the CACNA1A, CACNA1C, and CACNA1H genes were selected based on their reported associations with neurodevelopmental disorders and epilepsy." (PMID 40725423, 2025). "Our review has further revealed variants in CACNA1C, CACNA1F, CACNA1I, CACNA2D1 and CACNA2D2 as additional genes related to epilepsy." (PMID 33985586, 2021). "It has been reported, in a mouse model of ataxia and epilepsy, that cerebellar calcium channel proteins such as Cav1.2 were significantly reduced in number, and thus we speculate that CACNA1C is associated with cerebellar ataxia." (PMID 31291898, 2019). "We observed the upregulation of genes such as cacna1aa, cacna1c, cacna1da encoding the calcium channel subunits Cav2.1, Cav1.2, and Cav1.3, whose GOF mutations in humans lead to excessive Ca2+ entry and increased neuron excitability causing developmental disorders such as epilepsy or ASD." (PMID 40649845, 2025). "Interestingly enough, gain-of-function mutations of CACNA1D (which is the gene coding for Cav1.3) but not of CACNA1C (coding for Cav1.2) have been linked to epilepsy." (PMID 30699993, 2019). "This study focused specifically on three voltage-gated calcium channel genes—CACNA1A, CACNA1C, and CACNA1H—due to their well-established roles in neurodevelopmental disorders and epilepsy." (PMID 40725423, 2025). "Ultimately, 5 target genes were obtained, of which P2RX7 and TMTC2 were upregulated and CACNA1C, JPH3 and GRM1 were downregulated in epilepsy." (PMID 38191407, 2024). "This review delves into the significance of the CACNA genes, including CACNA1A, CACNA1B, CACNA1C, CACNA1D, CACNA1E, CACNA1G, and CACNA1H, in the pathogenesis of conditions such as migraine, epilepsy, cerebellar ataxia, dystonia, and cerebellar atrophy." (PMID 38785745, 2024). "Our review has highlighted CACNA1C, CACNA1F, CACNA1I, CACNA2D1 and CACNA2D2 as additional genes for epilepsy, and CACNA2D1 for autism spectrum disorder." (PMID 33985586, 2021).
epilepsy (continued). "Validating the concept that these 28 epilepsy-like CYFIP1KD DEGs are good disease gene candidates, a post-analysis literature review determined that CACNA1C and MT-ATP6, although not included in our training set, are in fact known to cause epilepsy." (PMID 26824476, 2016).
atrial fibrillation (20 papers, 2015 to 2025). A disorder characterized by an electrocardiographic finding of a supraventricular arrhythmia characterized by the replacement of consistent P waves by rapid oscillations or fibrillatory waves that vary in size, shape and timing and are accompanied by an irregular ventricular response. "In C57BL/6 mice, IL-1β inhibits QKI expression in cardiomyocytes, reducing the mRNA stability of CACNA1C, leading to downregulation of ICa-L, and inducing electrical remodeling and increased susceptibility to atrial fibrillation." (PMID 41561130, 2025). "In patients with atrial fibrillation, overexpression of miR-29a-3p found in the biopsies collected from the right atrial appendage during the general surgical procedure was associated with underexpression of calcium voltage-gated channel subunit alpha 1C (CACNA1C)." (PMID 30717412, 2019). "One study revealed that the overexpression of lncRNA KCNQ1OT1 mediated the upregulation of L-type Ca2+ channels, CACNA1C, by binding miR-384 in angiotensin-II induced atrial fibrillation." (PMID 37709486, 2023). "As a result of TaqMan qPCR and Western analysis, the relative mRNA and protein expression level of three target genes (DIER-1, TIMP-4 and CACNA1C) were significantly lower in the atrial fibrillation group than that in the healthy control group." (PMID 26319023, 2015). "This is in line with observations in a canine model of atrial fibrillation induced by rapid pacing for 1, 7, and 42 days in which a continuous decrease in ICaL density in atrial cardiomyocytes was observed over the period investigated as well as a decrease in mRNA expression of cacna1c." (PMID 36995425, 2023). "Chronic atrial fibrillation (CAF) raises miR-21 concentrations in human atrial myocytes, directly suppressing the subunits of L-type calcium channels (CACNA1C and CACNB2)." (PMID 41226851, 2025). "MiR-328 was reported to target CACNA1C/Cav1.2 and miR-30d could target KCNJ3/Kir3.1, which could lead to adverse electrical remodeling in atrial fibrillation." (PMID 33421993, 2021). "In addition to displaying cardinal features of CACNA1C disorders including LQTS, congenital heart disease, HCM, and sudden cardiac death, family members manifested atrial fibrillation and sick sinus syndrome." (PMID 33797204, 2021).
diabetes (19 papers, 2015 to 2025). "In fact, it has been reported that CLZ response and diabetes mellitus share genetic mechanisms, including recurrent genes such as CACNA1C in common pathways (e.g., insulin secretion)." (PMID 33557049, 2021).
autism spectrum disorder (17 papers, 2013 to 2025). A spectrum of developmental disorders that includes autism, and Asperger syndrome. "Calcium dysregulation has been associated with both monogenic and inherited autism spectrum disorders, with various mutations, such as in the CACNA1C gene, impairing neurodevelopment." (PMID 40142630, 2025). "In addition, a significant enrichment among the nominal DEGs for genes implicated in autism spectrum disorder (ASD) was found (e.g., AFF2, DNER, DPP6, DPP10, RELN, CACNA1C), as well as several that are strong candidate genes for the development of eye problems found in LS, including glaucoma." (PMID 32393163, 2020). "Besides, CACNA2D1 is related to autism spectrum disorder while CACNA1A, CACNA1C and CACNA2D1 are candidate genes for attention deficit hyperactive disorder." (PMID 33985586, 2021).
Cognitive impairment (16 papers, 2014 to 2026). Abnormal cognition is characterized by deficits in thinking, reasoning, or remembering. "The finding that either inadequate or excessive L-type calcium channel activation reduced neuronal firing explains why either loss- or gain-of-function variants in CACNA1C were associated with increased risk of cognitive disorders." (PMID 38776078, 2024). "This study evaluates the role of CACNA1C variants in altered prefrontal neurons in cognitive disorders." (PMID 38776078, 2024). "Genetic studies of mental disorders consistently find increased risk of cognitive deficits and mental illness with variants in CACNA1C, the gene that encodes the α1 subunit of the L-type calcium channel (LTCC) Cav1.2." (PMID 38776078, 2024). "The hippocampal overexpression of miR-499-5p in Cacna1c+/− rats caused memory impairments, recapitulating the cognitive deficits encountered in MD, including deficits in attention, memory and executive functions present during the different mood phases and during remission." (PMID 40065182, 2025). "A recent transgenic animal study suggested that deletion of Cacna1c in forebrain glutamatergic neurons during embryonic development, but not adulthood, was associated with hyperactivity, impaired hippocampal synaptic plasticity, cognitive impairment and reduced sociability." (PMID 31712549, 2019).
cardiomyopathy (15 papers, 2013 to 2026). A disease of the heart muscle or myocardium proper. "Several calcium ion channels involved in cardiomyopathies are associated with TOP2B peaks including the voltage-dependent calcium channel CACNA1C, the sarcoplasmic reticulum calcium release channel RYR1, and the Na+/Ca+ exchanger and calcium anti-porter SLC8A1." (PMID 26459242, 2015). "Thus, mutations in MXEs have been shown to cause diseases such as Timothy syndrome (missense mutation in the CACNA1C gene), cardiomyopathy (defect of the mitochondrial phosphate carrier SLC25A3) or cancer (mutations in, e.g., the pyruvate kinase PKM and the zinc transporter SLC39A14)." (PMID 29242366, 2017). "Cacna1c is an important gene for several signaling pathways (ASC, calcium, cAMP, cGPM-PKG, MAPK), all five types of synapses, as well as CMC, and the cardiomyopathies (DIL and HCM)." (PMID 38534766, 2024).